STAT3 (signal transducer and activator of transcription 3)
Diseases named in the same sentence as STAT3 in open-access papers (continued):
Sharing a sentence is not in itself a finding about the gene and the disease.
cyst (16 papers, 2016 to 2026). A sac-like closed membranous structure that may be empty or contain fluid or amorphous material. "Two positive feedback loops that integrate renal inflammation in cyst development were established: SMYD2/IL-6/STAT3/SMYD2 and SMYD2/TNF-α/NF-κB/SMYD2." (PMID 41431718, 2026). "In the Han:SPRD (cy/+) rat model of PKD, lodged calcium-phosphate microcrystals induce tubule dilation and cyst formation through the activation of the mammalian target of rapamycin (mTOR) and signal transducer and activator of transcription 3 (STAT3)." (PMID 37985930, 2024). "To test the role of individual STATs in type III encystment, we used previously generated STAT3, 5a, and 6 Lentiviral-mediated knock-down HFFs in a cyst assay." (PMID 37068104, 2023). "Two STAT3 inhibitors, pyrimethamine and S3I-201, also inhibited cyst growth in a neonatal and an adult Pkd1 model." (PMID 36120538, 2022). "STAT3 is shown to be strongly activated in cyst-lining epithelial cells in human ADPKD and in several PKD rodent models, compared with normal kidneys." (PMID 35867829, 2022). "A recent study independently reported similar STAT3 inhibition and overall reduced cyst growth with FTY720 treatment in the Cy/+ Han:SPRD rat model." (PMID 35867829, 2022). "In summary, we show increased activation of SRC and STAT3 in cyst‐lining epithelia of ARPKD kidneys." (PMID 33112055, 2020). "We show that the C‐term of human FC can regulate SRC‐activation and that SRC and STAT3‐activation can be observed in ARPKD cyst‐lining epithelial cells." (PMID 33112055, 2020). "To study the ability of the JAK2/STAT3 pathway to drive cystogenesis we performed cystogenesis assays in vitro using a monoculture grown in three dimensions (3D cyst assays)." (PMID 30872773, 2019). "Relevant to this point, a number of studies have shown that inhibitors of STAT3 activation have efficacy in restraining cyst expansion when administered to mice that model PKD." (PMID 27491076, 2016). "To explore the molecular mechanism of cyst formation induced by the abnormal activity of IL-6/JAK/STAT3 signaling pathway, we focused on FOSL1, a target gene of the IL-6/JAK/STAT3 signaling pathway, whose gene expression was greatly increased in xCEP290 morphant kidney in our RNA-seq analysis." (PMID 40570958, 2025). "Importantly, we show that FTY720 treatment is less effective in PKCζ null versions of these PKD mouse models, elucidating a PKCζ-specific mechanism of action that includes inhibiting STAT3 activity and cyst-lining cell proliferation." (PMID 35867829, 2022). "To study whether JAK/STAT in indeed activated in cells grown in 3D cyst assay and investigate if curcumin is able to block STAT3 phosphorylation, we performed immunoblotting from cyst assays." (PMID 30872773, 2019). "Further, the effectiveness of the STAT3 inhibitors in restraining cyst expansion and PKD progression could be due, at least in part, to inhibitory effects on the STAT3-dependent pro-proliferative functional phenotype of these macrophages." (PMID 27491076, 2016). "Phospho-STAT3-staining in the nucleus could also be detected within scattered cyst epithelial cells, as has been noted previously by several groups." (PMID 27491076, 2016). "The activation of nuclear factor kappa B (NF-κB) and STAT3 pathways, along with suppressed nuclear factor erythroid 2-related factor 2 (Nrf2) signaling and increased oxidative stress, up-regulates inflammatory cytokines and chemokines, driving cyst growth, inflammation, and fibrosis." (PMID 41431718, 2026). "To find out how curcumin blocks STAT3 activity we studied JAK2, which is highly expressed by cyst-lining cells in vivo and is known to activate STAT3 by phosphorylation." (PMID 30872773, 2019). "On the other hand, Stat3 activation, known to be involved in cyst growth 27, was not significantly different between the two genotypes, supporting the idea that Fjx1 role is related to the inflammatory/fibrotic response and not to cyst formation." (PMID 31038742, 2019).
cyst (continued). "Rop16-type I/III, but not type II, phosphorylates host STAT3 and STAT6, promoting early M2 macrophage polarization and reduced IL-12 secretion, favoring cyst formation." (PMID 41472067, 2025).
pituitary adenomas (16 papers, 2012 to 2025). "In the current study, it was demonstrated that the reduced expression of IL6 and STAT3 was associated with pituitary adenoma immune abnormalities." (PMID 25360166, 2014). "The STAT3 inhibitor S3I-201 decreases the growth of GH-producing pituitary adenoma cells both in vitro and in vivo in a concentration-dependent manner." (PMID 39139281, 2024). "As the results in module one demonstrated, the direct combined action and coadjustment between IL-6 and STAT3 was observed on pituitary adenoma development." (PMID 25360166, 2014). "BCL6 is essential in pituitary adenoma due to interactions with several factors, including STAT3, IL-6 and JUNB." (PMID 25360166, 2014). "Interestingly, IL6R signaling through the JAK2/STAT3/MMP9 axis was previously reported to promote the invasion of pituitary adenoma cells." (PMID 40002253, 2025). "Low expression levels of IL-6 and STAT3 were significant in the dysimmunity of pituitary adenoma." (PMID 25360166, 2014). "The low expression of IL-6 and STAT3 was important in the dysimmunity of the pituitary adenoma." (PMID 25360166, 2014). "STAT3 and VEGF, on the other hand, induce angiogenesis in pituitary adenomas and also play a positive role in bone growth and reconstruction." (PMID 36316863, 2022). "Atiprimod, an anticarcinogenic agent targeting STAT3, was effective in apoptotic induction in GH3 pituitary adenoma cells, a model of the lactotroph cell." (PMID 34681905, 2021). "Importantly, the knockdown of β-Catenin inhibited pituitary adenoma cell proliferation and migration probably by inhibiting AKT, STAT3, Cyclin D1, CDK4, MMP-2, and MMP-9." (PMID 35928898, 2022). "The PPI network of the downregulated DEGs in pituitary adenoma exhibited centralization, and certain node proteins of the network, including EGR1, STAT3, JUNB and FOS, were the common transcription factors in cancer; the PPI network of upregulated DEGs was sparsely populated." (PMID 25360166, 2014).
rosacea (16 papers, 2021 to 2026). A chronic erythematous skin disorder that affects the face. "Recently, signal transducer and activator of transcription factor 3 (STAT3) overexpression has been implicated in skin barrier dysfunction in Rosacea." (PMID 38193038, 2023). "Notably, a study identified STAT3 as a key gene linked to rosacea and skin barrier dysfunction using weighted gene coexpression network analysis (WGCNA)." (PMID 39044833, 2024). "Our findings establish MMT as a driver of fibrotic remodeling in rosacea, define STAT3 palmitoylation as a therapeutic target, and position BA as a dual-acting candidate for mechanism-based intervention." (PMID 41800255, 2026). "In summary, our study identifies the TLR2/MyD88/JAK2/STAT3 signaling pathway as a critical mediator of mast cell activation and degranulation in rosacea." (PMID 41383625, 2025). "By elucidating the intricate interplay between LL37, TLR2, and JAK2/STAT3 signaling in mast cells, our findings provide novel mechanistic insights into rosacea pathogenesis and lay the groundwork for the development of targeted therapies." (PMID 41383625, 2025). "Rosacea’s inflammation and immune infiltration are exacerbated by skin barrier disruption, partly due to STAT3-mediated cytokine signaling in keratinocytes." (PMID 39351216, 2024). "For example, one Janus Kinase- signal transducer and activator of transcription (JAK/STAT) proteins, STAT3, has been shown to have significant upregulation in expression in rosacea patients compared to healthy controls." (PMID 38193038, 2023). "Ultimately, skin barrier dysfunction is implicated in all phenotypes of rosacea and future therapies should target new pathogenic insights such as the roles of STAT1 and STAT3." (PMID 38193038, 2023). "Given the documented interactions between STAT3 and other inflammatory pathways such as VEGF and YAP/TAZ in endothelial and epithelial cells, it is possible that CBG’s suppression of STAT3 contributes to its broader anti-angiogenic and anti-inflammatory effects in rosacea." (PMID 40725084, 2025). "These evidences indicate that STAT3 may be an important gene in the pathogenesis of rosacea and acne, and it remains to be confirmed whether medications that target STAT3 may effectively treat rosacea and acne." (PMID 38321132, 2024). "STAT3 contributed to skin barrier dysfunction patterns-related immune infiltration in rosacea." (PMID 38193038, 2023). "Collectively, these data suggest that AQP3 plays an important role in regulating Th17 cell differentiation, which may be mediated by STAT3 activation in the context of rosacea." (PMID 37928265, 2023). "Central hubs such as STAT3, NF-κB, and oxidative pathways appear particularly promising as therapeutic targets, and their further investigation may ultimately enable the development of precise, mechanism-based interventions for rosacea." (PMID 41373451, 2025). "Transcriptomic analyses have identified STAT3 as a central regulatory node in rosacea skin, and experimental models have confirmed that LL-37 induces upregulation of JAK1, STAT3, and phosphorylated STAT3 in murine lesions." (PMID 40725084, 2025). "In rosacea, we found that the JAK2/STAT3 signaling pathway is significantly activated in mast cells and LL37-induced skin lesions." (PMID 41383625, 2025). "The expression of CXCL10, MMP9, IL1B, CXCL8, and CXCR4 were co-regulated by IRF1, STAT1, STAT3, IKBKB, HDAC1, ETS1, and CEBPB, which were highly expressed in rosacea and acne lesions." (PMID 38321132, 2024). "In LL37-treated HaCaT cells, elevated JAK2 and STAT3 levels suggest a strong connection between JAK/STAT signaling and rosacea’s inflammatory response." (PMID 39351216, 2024). "In vivo experiments further revealed that skin barrier dysfunction significantly elevates STAT3 expression and augments CD4+ T-cell infiltration in LL37-induced rosacea-like lesions in mice." (PMID 39044833, 2024).
rosacea (continued). "The infiltration of CD4+ T cells and the expression of Stat1, Stat3, and IL-17A were repressed by EGCG treatment in rosacea-like mice." (PMID 36937834, 2023). "Our findings reveal that AQP3-mediated activation of NF-κB in keratinocytes and activation of STAT3 in CD4+ T cells acted synergistically and contributed to the inflammation in rosacea." (PMID 37928265, 2023). "In rosacea patients, the increased levels of IL-6 correlate with ROS production and activation of the hypoxia-induced factor HIF-1α, and both effects are mediated through the IL-6/JAK/STAT3 pathway." (PMID 40006535, 2025).
acute lymphoblastic leukemia (15 papers, 2014 to 2026). Leukemia with an acute onset, characterized by the presence of lymphoblasts in the bone marrow and the peripheral blood. "The conserved aspartic acid residue D661 within the STAT3 SH2 domain is a recurrent mutational hotspot in hematologic malignancies, including T‐cell large granular lymphocytic leukaemia, myelodysplastic syndromes and acute lymphoblastic leukaemia." (PMID 41527523, 2026). "Interestingly, LINC00265 has been also shown to promote metastasis of acute lymphoblastic leukemia by regulating STAT3 signaling." (PMID 38948024, 2024). "Here, using murine models of GVHD, we show that STAT3–/– donor T cells induced only mild reversible acute GVHD while preserving GVL effects against nonsusceptible acute lymphoblastic leukemia (ALL) cells in a donor T cell dose–dependent manner." (PMID 37526084, 2023).
bladder tumors (15 papers, 2015 to 2026). "Recently, SMARCB1 (switch/sucrose nonfermentable-related matrix-associated actin-dependent regulator of chromatin subfamily B member 1), which encodes INI-1 (integrase interactor 1) loss, was found to drive bladder tumor progression via activation of the IL6/STAT3 axis." (PMID 39273033, 2024). "Downstream IL-6 signaling JAK1, STAT3, and SOCS3 were consistently upregulated in the same bladder tumors with low IL-6 levels suggesting IL-6 independent activation of the JAK1/STAT3 pathway." (PMID 29242529, 2017). "Our data indicates that Blcap is a novel Stat3 interaction partner and suggests a role for Blcap in the Stat3-mediated progression of precancerous lesions to invasive tumors of the bladder." (PMID 29190807, 2017). "In addition, IL-22 has been shown to promote PD-L1 expression through the activation of STAT3, and the anti-PD-L1 antibody nivolumab has been reported to be effective in bladder tumors with a high density of intratumoral IL22-producing cells." (PMID 38026978, 2023). "Therefore, the ETK over expression can be the reason of increased AKT and STAT3 activity in bladder tumors." (PMID 32795296, 2020). "Additionally, BLCAP was discovered to interact with STAT3 physically and may involve the STAT3-mediated progression of precancerous lesions to invasive bladder tumors." (PMID 35063012, 2022). "Within the bladder tumour microenvironment, systemic inflammatory disturbances enhance oncogenic signalling cascades such as COX-2, JAK/STAT3, and NF-κB, thereby fostering epithelial-mesenchymal transition, angiogenesis, and potential resistance to therapy." (PMID 41737225, 2026). "Suppression of ETK in bladder tumors reduced activity of AKT and STAT3." (PMID 32795296, 2020).
chondrosarcoma (15 papers, 2016 to 2024). A malignant cartilaginous matrix-producing mesenchymal neoplasm arising from the bone and soft tissue. "The gain-of-function and loss-of-function experiments were performed on chondrosarcoma cell lines to investigate the effects of miR-125b on chondrosarcoma invasion, and to determine whether signal transducer and activator of transcription 3(Stat3) mediates these effects." (PMID 27576314, 2016). "STAT3, a central regulator of tumor cell metabolism, emerges as a potential target in chondrosarcoma due to its involvement in multiple pro-tumorigenic pathways." (PMID 38542153, 2024). "Similar to miR-21-5p, miR-454-3p, another down-regulated miRNA in chondrosarcoma tissues, exerts a regulatory effect on STAT3." (PMID 38542153, 2024). "This convergent targeting of STAT3 across different pathways highlights its potential as a focal point for developing novel, targeted therapies against chondrosarcoma." (PMID 38542153, 2024). "Decreased miR-21-5p levels fuel chondrosarcoma progression by activating the CCR7/STAT3/NF-κB axis, promoting proliferation, migration, and invasion." (PMID 38542153, 2024). "In chondrosarcomas, resveratrol has been observed to decrease cell viability and proliferation, promote apoptosis, and inhibit STAT3 signaling, contributing to tumor suppression." (PMID 39590345, 2024). "MiRNAs, such as miR-21-5p and miR-454-3p, also influence pathways crucial for tumor proliferation and survival, including the STAT3/NF-κB axis, whose activation drives chondrosarcoma progression." (PMID 39590345, 2024). "We were able to demonstrate, especially in Cal78 chondrosarcoma cells, a significant reduction of STAT3 phosphorylation after treatment with all shikonin derivatives." (PMID 35820864, 2022). "In chondrosarcoma, increasing hsa-miR-454-3p can downregulate Stat3 and Atg12 to inhibit chondrosarcoma growth." (PMID 29744354, 2018). "Taken together, this study reveals for the first time that miR-454-3p increases after HOTAIR knockdown to inhibit chondrosarcoma cell growth by targeting Stat3 and Atg12." (PMID 28182000, 2017). "For the first time, we report that miR-454-3p functions as an anti-oncogene in chondrosarcoma cells by targeting Stat3 and Atg12." (PMID 28182000, 2017). "In line with the in vitro data, ATO increased the E-cadherin expression and decreased the p-Stat3, vimentin and N-cadherin expression in tumors formed by chondrosarcoma cells." (PMID 27576314, 2016). "The present study, for the first time, provides evidence that the miR-125b-mediated inhibition of Stat3 is involved in the ATO-induced attenuation of metastasis in chondrosarcoma cells." (PMID 27576314, 2016). "We detected a direct binding of miR-125b to the 3’UTR of Stat3 with a dual-luciferase reporter assay and observed significant downregulation of Stat3 in miR-125b-overexpressing chondrosarcoma cells." (PMID 27576314, 2016). "Together, these findings strongly indicate that ATO inhibits EMT and invasive capacity through the miR-125b/Stat3 axis in chondrosarcoma cells." (PMID 27576314, 2016). "We also found that miR-125b knockdown up-regulated Stat3 expression and rescued siRNA-mediated Stat3 suppression in chondrosarcoma cells." (PMID 27576314, 2016). "Other promising treatments include MLN4924, a NEDD8-activating enzyme inhibitor, which has shown antitumor effects in both cell lines and a xenograft mouse model, and resveratrol, which inhibited cell viability and suppressed the STAT3 signaling pathway in chondrosarcoma cells." (PMID 39590345, 2024). "Since it has been demonstrated that IL-1 inhibits STAT3’s chromatin accessibility in a chondrosarcoma cell line, IL-21 may reverse this inhibition and induce the proliferation of IL-1-stimulated Vγ4+nγδT17 cells but not Vγ6+nγδT17 cells." (PMID 37662923, 2023).
chondrosarcoma (continued). "Furthermore, we demonstrated that miR-125b inhibited the EMT process in chondrosarcoma cells by targeting signal transducer and activator of transcription 3 (Stat3); constitutive activation of Stat3 is a key player in tumor angiogenesis and metastasis." (PMID 27576314, 2016). "We examined the effects of ATO on the activation of Stat3 in chondrosarcoma cells." (PMID 27576314, 2016). "Furthermore, decreased miR-21-5p levels contribute to chondrosarcoma cell proliferation, migration, and invasion through activation of the CCR7/STAT3/NF-κB pathway." (PMID 38542153, 2024). "Interestingly, increased expression of the long non-coding RNA HOTAIR leads to miR-454-3p up-regulation, subsequently suppressing STAT3 and ATG12, triggering apoptosis, decreasing autophagy, and inhibiting chondrosarcoma cell growth." (PMID 38542153, 2024). "There have been numerous studies on the anti-inflammatory effects of GPS; however, whether GPS ameliorates inflammation and chondrocyte hypertrophy in the LPS-induced SW 1353 chondrosarcoma cells via the Stat3/Runx2 signaling pathway has not been reported." (PMID 38528538, 2024). "Corresponding cellular mechanisms, the induction of apoptosis, and the regulation of mitogen-activated protein kinases (MAPKs) and signal transducer and activator of transcription 3 (STAT3) by shikonin derivatives in human chondrosarcoma cell lines have not yet been investigated." (PMID 35820864, 2022). "Herein, in ATO-treated chondrosarcoma cells, for the first time, we identified that miR-125b exhibited a tumor suppressor function, which attenuated the EMT and invasive capacities by targeting Stat3, which is activated to trigger the molecular events in the EMT of various human tumors." (PMID 27576314, 2016).